HBEGF (heparin binding EGF like growth factor)
Diseases named in the same sentence as HBEGF in open-access papers (continued):
Sharing a sentence is not in itself a finding about the gene and the disease.
tumor (194 papers, 1996 to 2026). "This co-regulation of VEGFA and HBEGF likely enhances vascular remodeling and tumor progression through complementary pathways, further reinforcing ICB resistance." (PMID 41514936, 2026). "We further identified that MES‐like cells sheltered in the vicinity of PECAM1+ tumor vascular niches correlated with local HBEGF upregulation." (PMID 41181988, 2026). "Consistent with our findings, HBEGF upregulation (approximately three‐fold) can be detected in stem‐like cell niches including microvascular and tumor leading edge, where plastic GSCs are typically found." (PMID 41181988, 2026). "Among them, VEGFA and HBEGF are known to exert central roles in driving tumor angiogenesis, while CXCL8 and its related chemokines positively regulate angiogenic processes." (PMID 41514936, 2026). "Cancer-associated fibroblasts signal to the cancer cells for tumour growth and angiogenesis via pathways such as HGF, ANGPTL4, HBEGF and FGF." (PMID 39149248, 2024). "The differential association of TSPAN29 (CD9) with CD315, CD316, epithelial cell adhesion molecule (EPCAM), claudin 1 and heparin-binding EGF-like growth factor (HB-EGF) can be related to the different effects on tumor cell invasion and metastasis." (PMID 32138170, 2020). "EREG prognostic value has been demonstrated, while HBEGF was shown to regulate tumor cell metastatic phenotype." (PMID 25122487, 2014). "BEX1 and FBLN were associated with ER, while FBLN1, HBEGF, KLK3, and TMPRSS2 were associated with tumor aggressiveness." (PMID 21134280, 2010). "Furthermore, transcription factors FOS and JUNB showed robust correlations with CXCL2 and HBEGF, suggesting multiple molecular mechanisms regulating tumor angiogenesis in Transitional Mono to M0 cells." (PMID 41514936, 2026). "In addition to this highly inflammatory phenotype, expression of other pro-inflammatory genes, such as IL1B, CXCL16, VEGFA and HBEGF, which can facilitate tumor progression and survival, were also observed." (PMID 41056512, 2025). "Additionally, genes associated with tumor cell apoptosis pathways showed overall activation, among which IRF7, DDIT3, and HBEGF were significantly activated." (PMID 38711992, 2024). "We found that HBEGF is positively correlated with hsa_circ_000200 in GC tissues, suggesting that HBEGF may played a role as a tumor promoter." (PMID 37525152, 2023). "Additionally, activation of epidermal growth factor receptor (EGFR) in MLPS tumor cells by macrophage-secreted ligand heparin-binding EGF-like growth factor (HB-EGF) plays a crucial role in this process." (PMID 36230502, 2022). "Evidence suggests that ADAM17 promotes tumor-associated macrophage polarization and angiotensin II-mediated pro-growth and pro-migration signals by shedding EGFR ligands, including heparin-binding EGF-like growth factor (HB-EGF) and AREG (members of the EGF family), from the cell membrane." (PMID 36466812, 2022). "The most common interaction with the receptor on the tumor cells was composed by the pair EGFR and HBEGF, which could tend to promote tumor growth." (PMID 33155039, 2020). "Transmigration of tumor cells through the BBB is mediated by the upregulation of three genes: (HBEGF (Heparin-Binding Epidermal growth factor-like Growth Factor), COX-2 (PTGS2, Prostaglandin-Endoperoxide-Synthase-2), and ST6GALNAC5 (ST6-N-Acetylgalactosaminide-Alpha-2,6-Sialyltransferase-5))." (PMID 32645833, 2020). "We also described the interaction between EGFR and HBEGF: the feedback loop between these 2 genes regulates astrocytes' maturation and promotes gliomagenesis in specific contexts; the silencing of 1 of the partners tends to reduce tumor growth and increases survival in vivo." (PMID 33155039, 2020). "Tumor-associated fibroblasts induce also the direct proliferation of keratinocytes, releasing a ligand of epidermal growth factor receptor (EGFR), namely heparin-binding EGF like growth factor (HBEGF), against which further studies may create monoclonal antibodies." (PMID 31096567, 2019).
tumor (continued). "Beyond their modulation of the tumor microenvironment, these macrophages directly stimulate tumor growth and induce epithelial–mesenchymal transition via the secretion of AREG (amphiregulin) and HBEGF (heparin-binding EGF-like growth factor)." (PMID 40092486, 2025). "We found that exposure to FGF2, FGF18, HBEGF, IGF1, PDGF-BB, and TGFα significantly (p < 0.0001) increased MCL1 expression in tumor cells (by at least 1.2-fold and up to 2-fold) and treatment with the MEKi reduced this response." (PMID 37676378, 2024). "Examination of the CCC TME revealed activation of several signalling pathways (HGF, ANGPTL4, HBEGF, and FGF) that promote tumour growth and angiogenesis." (PMID 39149248, 2024). "To see if LGALS9, HBEGF, and GRN mediate tumor-macrophage interactions and contribute to PDAC progression, we performed in vitro experimental studies for validation." (PMID 36864399, 2023). "MMP14 activity also triggers the proteolytic processing and activation of Heparin-Binding EGF-like growth factor (HB-EGF), which stimulates the EGFR signaling pathway and increases tumor proliferation and growth." (PMID 34976811, 2021). "Tumor cells expressed relatively high levels of EGFR, FGFR1, and FGFR2, while their corresponding ligands, such as COPA, GRN, HBEGF, FGF2, FGF7, and FGF18, were widely expressed in fibroblast cells." (PMID 34459128, 2021). "The main differences observed between the two types of hypoxia involved the expression of several genes such as IL-8, CXCL2, EPHA2, AREG, HBEGF, and PLAU, which are relevant to tumor progression." (PMID 25122487, 2014). "MiR-126&126* play their tumor suppression function through the direct inhibition of ADAM9 and MMP7, in turn impairing the activation of their common target heparin-binding EGF-like growth factor (HB-EGF)." (PMID 23437250, 2013). "Consistent with this, we found all angiogenesis-related genes to be significantly upregulated in non-pCR patients, with VEGFA, CXCL8, CXCL2, CXCL3, and HBEGF identified as core drivers of tumor angiogenesis and immune escape." (PMID 41514936, 2026). "The cancer cells secrete platelet-derived growth factor (PDGF)-D and TGF-β1, both of which activate CAFs, whereas CAFs secrete PDGF-B, heparin-binding EGF-like growth factor (HB-EGF), and stromal cell-derived factor-1 (SDF-1, also known as CXCL12), and thereby promote tumor growth and invasion." (PMID 37174001, 2023). "Also, LGALS9, HBEGF, and GRN were confirmed to be over-expressed in macrophage subset, highlighting the potential roles in mediating tumor-macrophage interactions." (PMID 36864399, 2023). "In the breast TME, tumor and stromal cells stimulate cytokine-mediated p38MAPK signaling that increases expression of pro-angiogenic and pro-invasive factors such as VEGFA, IL8, IL6, HBEGF, and Fibronectin." (PMID 28977919, 2017). "HB-EGF, Heparin-binding EGF-like growth factor, was found in the top 1% of half of the tumor types." (PMID 29057876, 2017). "Thus, in addition to overexpression of the EGF receptor, its ligands epidermal growth factor (EGF), transforming growth factor-α TGF-α, amphiregulin (AR), betacellulin (BTC), heparin-binding EGF-like growth factor (HB-EGF), and epiregulin (EREG) have been reported to be upregulated in tumor tissues." (PMID 31921216, 2019). "The EGFR ligands: epidermal growth factor (EGF), transforming growth factor-α (TGFA), heparin-binding EGF-like growth factor (HBEGF), amphiregulin (AREG), beta-cellulin (BTC), epiregulin (EREG) and epigen (EPGN), may increase tumor growth, invasion, and metastasis through EGFR activation." (PMID 27669890, 2016). "Tumor cell-secreted factors trigger two stereotype secretory profiles in peripheral blood monocytes and differentiated macrophages: monocytes secrete epiregulin (EREG) and oncostatin-M (OSM), while macrophages secrete heparin-binding EGF-like growth factor (HB-EGF) and OSM." (PMID 23597096, 2013).
tumor (continued). "Additionally, tumor cells secrete growth factors, metalloproteinases, and proteases to migrate through the BBB, such as prostaglandin-endoperoxide synthase 2 (COX2), the heparin-binding EGF-like growth factor (HB-EGF), matrix metalloproteinases (MMPs), and cathepsin S." (PMID 38002256, 2023).
cancer (121 papers, 2005 to 2026). A tumor composed of atypical neoplastic, often pleomorphic cells that invade other tissues. "We have found significant genes (SASH1, TBX2, HBEGF, etc.)linked to NSCLC cancer that can serve as potential drug targets." (PMID 37324026, 2023). "For example, cancer cells overexpress enzymes associated with mitogenesis and growth factors, including prostaglandin-endoperoxide synthase 2 (COX2) and heparin-binding EGF-like growth factor (HBEGF), allowing cell migration through the BBB." (PMID 36765679, 2023). "In this study, we investigated the effects of PM exposure on cancer metastasis and demonstrated that PM induces HBEGF expression in macrophages and that secreted HBEGF is crucial for mediating cancer cell metastasis through EMT." (PMID 36352257, 2022). "MMP-14 also increases cancer invasiveness by cleaving the N-terminal heparin-binding domain of heparin-binding EGF-like growth factor (HB-EGF) to convert it into a heparin-independent growth factor." (PMID 35008569, 2021). "To test PASTMUS strategy in mapping functional elements of proteins, we selected three genes (ANTXR1, CSPG4, and HBEGF) encoding bacterial toxin receptors and three genes (HPRT1, PLK1, and PSMB5) encoding cancer drug targets." (PMID 31842968, 2019). "Upregulation of HBEGF has been observed in several cancer cells including breast (MDA-MB-231) and prostate (PC3), and it has been suggested as a potential target for treatment." (PMID 27918443, 2016). "Furthermore, expression of HBEGF has been shown to be increased significantly in many human cancer types, and HBEGF mRNA expression has been shown to be increased two- to 5-fold in GB cell lines compared to control brain tissue." (PMID 39565278, 2025). "Moreover, we observed that at basal state, HBEGF is more expressed in cancer cells than in CAFs also in the different pairs of cancer cells – CAFs transcriptional data." (PMID 39262776, 2024). "To determine whether the increased level of HBEGF in PM-stimulated THP1 cells mediates the increase in the motility of cancer cells, we treated A549 CM-Con cells with recombinant human HBEGF (rhHBEGF)." (PMID 36352257, 2022). "Autocrine/paracrine production of epidermal growth factor receptor (EGFR) ligands, like epiregulin, amphiregulin, and heparin-binding EGF-like growth factor (HB-EGF), and the overexpression of EGFR, are two of the mechanisms most frequently implicated in cancer development and progression." (PMID 34360915, 2021). "Finally, AREG and HBEGF expression levels were positively correlated in the carcinomas." (PMID 27669890, 2016). "By altering HBEGF signaling in GB, HP‐NP induced the conversion of MES‐like GSCs into less plastic glial‐like cells, stopping resupply of new cancer stem cells and malignant propagation in the CNS." (PMID 41181988, 2026). "Increased transcripts of heparin-binding EGF-like growth factor (HBEGF), a positive regulator of the epidermal growth factor receptor, and protein kinase B gene might overstimulate stress response pathways and cell survival in a way that could be damaging to cancer cells." (PMID 37834191, 2023). "Similar to the potential cross-talk between mesothelial cells and cancer cells, we identified possible interactions between LA-TAMs/mesothelial cells by SPP1, RETN, LGALS9, NAMPT, and HBEGF secretion." (PMID 37649596, 2023). "LA-TAMs also participated in the modification of cancer cells by SPP1, VEGFA, RETN, GRN, ADGRE5, and HBEGF secretion." (PMID 37649596, 2023). "Results from our scRNA-seq analyses identified several potential interactions involving the cancer stem cell marker CD44 with ligands secreted by CAFs such as HGF, HBEGF, FGF2 and LGALS9." (PMID 36273171, 2022). "Recently, a study showed that heparan sulfate (HS)-instructed self-assembled peptides hinder the interaction between heparin-binding EGF-like growth factor (HB-EGF) and heparan sulfate proteoglycans (HSPG), thus inhibiting cancer cell migration." (PMID 36140068, 2022).
cancer (continued). "We found that PM enhances the expression of heparin-binding EGF-like growth factor (HBEGF) in macrophages, which induces epithelial-to-mesenchymal transition (EMT) in cancer cells, thereby increasing metastasis." (PMID 36352257, 2022). "Among significantly positive miRNA-mRNA pairs correlation covering at least 10 cancer types, 2 pairs from our list can be found: hsa-miR-486-5p~HBB and hsa-miR-223-3p~HBEGF." (PMID 34320033, 2021). "HBEGF is a ligand for EGFR that was shown to increase migration and invasiveness of cancer cells and was identified specifically in brain metastasis compared to the bone and lung." (PMID 32645833, 2020). "HBEGF, a ligand for EGFR (Epidermal Growth Factor Receptor), was shown to increase invasiveness of cancer cells to the brain." (PMID 32645833, 2020). "CAFs secrete a multitude of signalling molecules (such as IL-1β, PDGF-B, heparin-binding EGF-like growth factor and SDF1) that promote cancer progression by enhancing proliferation, survival, chemotaxis and angiogenesis." (PMID 32606456, 2020). "Immunoblotting analysis of cancer cell conditioned medium highlighted that ADAM9 regulates the levels of angiogenic factors, including shed heparin‐binding EGF‐like growth factor (HB‐EGF)." (PMID 30556643, 2019). "FZD8, plasminogen activator, urokinase receptor, ITGA2, WNT2B, TIMP3, WNT5B, FGF5, heparanase, HBEGF and WNT3A were up-regulated in the proteoglycan pathways in cancer, whereas WNT10A, PIK3R3, IGF2 were down-regulated." (PMID 30482199, 2018). "For example, the EGF-family ligands heparin-binding EGF-like growth factor, amphiregulin, and TGF-α are upregulated in cancer cells from many different cancer types, and TGF-α overexpression causes widespread epithelial hyperplasia in mice." (PMID 22242000, 2011). "Ingenuity analysis identified a group of 7 genes (BEX1, FBLN1, FGD3, HBEGF, KLK3, KLK6, and WNT5B) related to cancer, cellular function and maintenance, cellular growth, invasion, as well as proliferation with P < 0.001-0.05." (PMID 21134280, 2010). "The identified up-regulated genes with H3K27Ac engagement included the inflammatory response genes IL1α, IL1β, and SERPINB2; the HBEGF gene that mediates cell migration and invasion; PLAU, which is regulated by AP-1 and drives cancer metastasis; and LAMC2, which is involved in the EMT process." (PMID 37511268, 2023). "The growth factor HBEGF, which is highly expressed in Monocytes, Neutrophils, Dendritic Cells, GMP Cells, Macrophages, and various Epithelial Cells, interacts with CD9 expressed in Cancer Cells to help mediate tumorigenesis and proliferation." (PMID 36401283, 2022). "Notably, EGFR and its receptors, including TGFB1, MIF, HBEGF, GRN, COPA, and AREG, were upregulated in cancer cells and fibroblasts." (PMID 34326696, 2021). "Interaction of microbes, such as H. pylori, with host cells modulates host cell signaling pathways involved in the promotion of cancer, such as mitogen-activated protein kinase (MAPK) pathway, integrin-mediated signaling, and heparin-binding EGF-like growth factor (HB-EGF) pathways." (PMID 29558443, 2018). "Since cancer extracellular matrix releases EGF and HBEGF, and AREG correlated to HBEGF expression, we hypothesized that extracellular EGF and/or HBEGF induced AREG overexpression in OSCC." (PMID 27669890, 2016). "Additionally, HBEGF, an EGFR ligand intensively involved in cancer progression, was shown to be the main mediator of epithelial cells and AM cells affecting other cell types, and may serve as a potential target for early stage LUAD treatment." (PMID 37957625, 2023). "ADAM17 proteolytically cleaves and activates several EGFR ligands such as epiregulin, transforming growth factor alpha (TGF-alpha), amphiregulin (AREG) and heparin-binding EGF-like growth factor (HB-EGF) and may thus contribute to cancer progression through EGFR activation." (PMID 36140519, 2022).
cancer (continued). "EGFR is overepressed in many cancer types and activated by a variate of ligands, including besides EGF also the transforming growth factor-alpha (TGFA), heparin-binding EGF-like growth factor (HBEGF), betacellulin (BTC), amphiregulin (AREG) and epiregulin (EREG) and epigen (EPGN)." (PMID 32119655, 2020).
infection (25 papers, 2008 to 2025). The state of being infected such as from the introduction of a foreign agent such as serum, vaccine, antigenic substance or organism. "Module 2 focused on epithelial barrier function and growth factor signaling, identified EREG, FGFR2, and MET as central hubs, alongside AREG and HBEGF, which support epithelial repair and regeneration after infection-induced damage." (PMID 40634947, 2025). "A larger overlap in DEGs was noted between the two time points in the infection group with 74 DEGs that enriched to processes involved in wound repair (HBEGF and MT2A) as well as immune responses to pathogens (CCL20, IL6, and SLAMF1)." (PMID 40576342, 2025). "Here we found that genes IRS2, NRG1, HBEGF, and EREG regulating AKT signaling are downregulated in M-MDSC isolated from CoV2+ participants long after recovery from infection." (PMID 35812392, 2022). "infection, whereas the corresponding early responding genes in SCC cells were IL10, IL1β, IL1α, TNF, CXCL10, CXCL1, HBEGF, IL6, and CSF3." (PMID 31912662, 2020). "The infection behavior of pilTL201C is also defective, due to its inability to activate the EGFR-heparin-binding EGF-like growth factor (HB-EGF) pathway." (PMID 27923924, 2016). "The infection behavior of pilTL201C is also defective, due to its failure to activate the epidermal growth factor receptor (EGFR)-heparin-binding EGF-like growth factor (HB-EGF) pathway." (PMID 27923924, 2016).
adenocarcinoma (4 papers, 2015 to 2023). A common cancer characterized by the presence of malignant glandular cells. "Of the canonical changes noted, promoter (PR) DM loci with reciprocal changes in expression in adenocarcinomas included HBEGF, AGER, PTPRM, DPT, CST1, MELK; DM GB loci with concordant changes in expression included FOXM1, FERMT1, SLC7A5, and FAP genes." (PMID 26683690, 2015).
cardiovascular disease (2 papers, 2017). "The upregulated expression of heparin binding EGF-like growth factor (HB-EGF) in the vessel and circulation is associated with risk of cardiovascular disease." (PMID 28792970, 2017).
immune disorders (1 paper, 2025). "The high expression of differentially expressed genes, such as TLR4, CXC-8, PLA2/G7, HBEGF and FABP2, and the overactivation of immune pathways shown by GSEA prove that immune disorders are involved in the onset of NEC." (PMID 38814387, 2025).
HBEGF also shares sentences with these, for which no sentence is quoted: melanoma (9 papers); cervical cancer (6); kidney diseases (5); pterygium (5); Stroke (5); cholangiocarcinoma (4); colitis (4); Hydrocephalus (4); Insulin resistance (4); lung adenocarcinoma (4); Autoimmunity (3); bacterial infection (3); crescentic glomerulonephritis (3); hepatocellular carcinoma (3); Hypertension (3); polycystic ovary syndrome (3); rapidly progressive glomerulonephritis (3); subarachnoid hemorrhage (3); acute kidney injury (2); age-related macular degeneration (2); Anxiety (2); autoimmune disease (2); CADASIL (2); cardiac disease (2); cyst (2); diabetes (2); diabetic kidney disease (2); diphtheria (2); E. coli infection (2); emphysema (2).
A further 128 diseases each share a sentence with HBEGF in 2 papers or fewer.